CXCR5 (C-X-C motif chemokine receptor 5)
Diseases named in the same sentence as CXCR5 in open-access papers (continued):
Sharing a sentence is not in itself a finding about the gene and the disease.
follicular lymphoma (6 papers, 2018 to 2023). Follicular lymphoma is a form of non-Hodgkin lymphoma characterized by a proliferation of B cells whose nodular structure of follicular architecture is preserved. "In the follicular lymphoma (FL) microenvironment, CXCR5+ICOS+PD1+BCL6+ follicular helper T (Tfh) cells, which closely correlate with FL B cells in neoplastic follicles, play a major role in supporting FL." (PMID 34069564, 2021). "To tackle the follicular nature of CD4+ T cells in the lymphoid aggregates, we performed IF stainings of CD4, CXCR5 together with NFATc1, again after having established detection on tonsils, follicular lymphoma of the spinal cord, and PCNSL of the brain." (PMID 32010141, 2019). "Interestingly, superior cell survival and effector functions were reported in CXCR5+ T cells from follicular lymphoma patients." (PMID 37388744, 2023). "CXCR5+CD8 T cells correlate with disease-free or overall survival in pancreatic, colon, follicular lymphoma, gastric, high-grade serous ovarian, hepatocellular, and bladder cancers and thus is considered a potential biomarker." (PMID 36314014, 2022).
lupus nephritis (6 papers, 2015 to 2025). Glomerulonephritis in the context of systemic lupus erythematosus. "CXCR5− Tfh‐like cells have been observed in several end‐organ sites of inflammatory pathology, including rheumatoid synovitis, lupus nephritis and sarcoidosis pneumonitis." (PMID 40469525, 2025). "Recently, CXCR5− IgD− CD27− double negative B cells (CXCR5− DNB) were shown to migrate to extrafollicular regions and are associated with lupus nephritis disease activity." (PMID 35997780, 2023). "Chemokines and chemokine receptors are used as therapeutic targets in lupus nephritis; therefore, we assessed the surface expression of the most important chemokine receptors (CCR6, CCR7, CXCR4 and CXCR5) on B lymphocytes from all four groups by flow cytometry." (PMID 25909640, 2015).
ovarian carcinoma (6 papers, 2013 to 2025). A malignant neoplasm originating from the surface ovarian epithelium. "In ovarian cancer, high CXCL13 expression is associated with prolonged survival by shaping the anti-TME by facilitating the maintenance of CXCR5+CD8+ T cells." (PMID 40406143, 2025). "Among different pathological types of ovarian cancers, there were various degrees of expression differences, except for CXCR5 and CXCR6, and the gold change ranged from 1.628 to 2.824." (PMID 33829065, 2021). "CXCR5 was the only CXC family member that not only related to the clinical stage of ovarian cancer, but also negatively correlated to the OS, PFS, and PPS of ovarian cancer patients." (PMID 33829065, 2021). "This suggests that CXCR5/6 is an important protective factor, while CXCR7 is a risk factor of ovarian cancer." (PMID 33829065, 2021). "Although CXCR5 promotes the growth of tumor cells in the liver, the role(s) of CXCR5 in ovarian cancer is poorly understood." (PMID 23800251, 2013). "However, the relationship between CXCR5 expression and ovarian cancer has rarely been reported." (PMID 33829065, 2021). "In ovarian cancer, combination therapy with CXCL13 and an anti-PD-1 antibody inhibited tumor growth in a CXCR5+CD8+ T-cell expansion-dependent manner." (PMID 40406143, 2025). "The results showed that CXCRs were expressed in both cell membrane and cytoplasm of ovarian cancer tissues, among which CXCR4 expressions were the highest, and CXCR3, CXCR5, CXCR6, and CXCR7 were expressed in different degrees." (PMID 33829065, 2021). "In preclinical models of ovarian cancer, intraperitoneal injection of recombinant CXCL13 could induce TLS formation, then inhibit tumor progression and enhance the efficacy of anti-PD-1 therapy through increased infiltration of CXCR5+ CD8+ T cells." (PMID 40352278, 2025). "As the cancer cells tested do not express CXCL13 (a ligand for CXCR5), the novel role of CXCR5 in ovarian cancer cells in response to EGF or TNF may highlight their interaction with immune cells expressing CXCL13 in the tumor microenvironment." (PMID 23800251, 2013). "CXCR1 and CXCR2 were downregulated in ovarian cancer tissues, while CXCR5 and CXCR6 were not significantly different between ovarian cancer and normal tissues." (PMID 33829065, 2021).
Clear Cell Renal Cell Carcinoma (5 papers, 2018 to 2026). "Also, CXCL13 through CXCR5 was shown to promote growth and invasion via the PI3K/AKT pathway in clear cell renal carcinoma." (PMID 33193299, 2020).
helminth infection (5 papers, 2013 to 2025). "Taken together, the data presented here support the conclusion that the CXCR5 is expressed by migratory DCs within the cDC2 compartment that responds to intestinal helminth infection by supporting development of the protective TH2 response." (PMID 41012147, 2025). "TLN Th2 cells were also defined as being CXCR5- to exclude CXCR5+ T follicular helper (Tfh) cells, which are IL-4gfp+ during helminth infection." (PMID 31815932, 2019). "Thus, CXCR5 expression by migratory DCs is important for development of protective TH2 immunity during helminth infection." (PMID 41012147, 2025). "It is possible that at later stages of immune activation during helminth infection, CXCR5 becomes more important for T cell polarization and for T follicular helper cell differentiation, while in the early stages of Th2 induction CCR7 plays a more dominant role." (PMID 28716804, 2017). "T follicular helper (Tfh) cells are IL-4gfp+ and express PD-1 during helminth infection, and as expected the increases in tLN IL-4gfp+ T cells observed during L. sigmodontis infection represented an expansion of both IL-4gfp+CXCR5− Th2 cells and IL-4gfphighCXCR5+ Tfh cells." (PMID 23516361, 2013).
inflammatory bowel disease (5 papers, 2021 to 2024). A spectrum of small and large bowel inflammatory diseases of unknown etiology. "For example, the inflammatory bowel disease–associated rs630923 variant is located within the promoter of the CXCR5 gene, which has EBNA2-dependent lower gene expression." (PMID 34799401, 2021).
Sepsis (5 papers, 2020 to 2025). Sepsis is defined as life-threatening organ dysfunction caused by a dysregulated host response to infection. "Our results further suggest that CXCR5 deficiency restores autophagy and inhibits microglia-induced neuroinflammation, ameliorating sepsis-induced cognitive dysfunction." (PMID 34711216, 2021). "Our previous work showed that CXCR5 contributes to learning and memory impairment in an animal model of sepsis." (PMID 33161894, 2020). "Additionally, potential implication of the CXCR5/p38MAPK axis in infection-induced sepsis should be explored in future studies." (PMID 34711216, 2021). "CXCR5 may act via p38MAPK/NF-κB/STAT3 signaling to inhibit hippocampal autophagy during sepsis and thereby contribute to cognitive dysfunction." (PMID 34711216, 2021). "In previous work, we showed that CXCR5 may inhibit proliferation, differentiation, and survival of hippocampal neuronal stem cells in an animal model of sepsis, leading to learning and memory impairments." (PMID 33161894, 2020). "Our results further suggest that down-regulating CXCR5 can restore autophagy, polarize microglia toward the M2 phenotype, and inhibit p38MAPK/NF-κB/STAT3 signaling, ultimately attenuating sepsis-induced neuroinflammation and cognitive dysfunction." (PMID 34711216, 2021).
age-related macular degeneration (4 papers, 2017 to 2020). Age-related loss of vision in the central portion of the retina (macula), secondary to retinal degeneration. "CXCR5 is a protective factor of retinal cells in aged mice and its loss leads to pathological changes similar to age-related macular degeneration (AMD)." (PMID 31355256, 2019). "However, the mechanisms through which chemokine receptor CXCR5 and ligand CXCL13 signal to regulate age-related macular degeneration have not been explored." (PMID 32492870, 2020).
diffuse large B-cell lymphoma (4 papers, 2019 to 2025). "In B cell lymphoma-bearing mice and diffuse large B cell lymphoma patients, CXCR5+ CD8 T cells likely arise to directly target cancer cells." (PMID 31275308, 2019).
juvenile dermatomyositis (4 papers, 2014 to 2024). Juvenile dermatomyositis (JDM) is the early-onset form of dermatomyositis (DM), a systemic, autoimmune inflammatory muscle disorder, characterized by proximal muscle weakness, evocative skin lesion, and systemic manifestations. "TfH cells that co-express Th17 markers (CXCR5+Th17) encompass both of these pathogenic functions, and are increased in some human autoimmune settings including juvenile dermatomyositis." (PMID 28004828, 2016).
multiple myeloma (4 papers, 2021 to 2023). "With the unbiased t-SNE plot analysis, it was visible that γδT cells were more abundant in myeloma patients, TCRγδ being co-expressed in part with CD4, CD8 or in the compartment of Tfh cells by co-expressing CXCR5." (PMID 37187728, 2023). "The B-ALL and multiple myeloma (MM) cell lines (NALM-6, REH, NCI-H929) derived from precursor B and plasma cells, respectively, lacked CXCR5 expression as does the T-ALL cell line Jurkat." (PMID 33431832, 2021).
multiple sclerosis (4 papers, 2018 to 2024). A progressive autoimmune disorder affecting the central nervous system resulting in demyelination. "The frequency of CXCR5+ T cells in these lesions is not yet clear; however, in cerebrospinal fluid from multiple sclerosis patients ~20% of memory CD4+ T cells express CXCR5, comparable to the frequency observed in blood." (PMID 30190721, 2018). "While the expression of CXCR5 may differ between cerebrospinal fluid and tissue, these observations raise the possibility that a large portion of the IL-21+ CD4+ T cells in multiple sclerosis may not express CXCR5." (PMID 30190721, 2018).
neuroblastoma (4 papers, 2015 to 2023). Neuroblastoma (NB) is the most common solid, extracranial childhood tumor. "CXCR5 is also expressed on bone marrow-metastatic neuroblastoma cells, which migrate toward CXCL13 in vitro, suggesting CXCL13/CXCR5 signaling may be involved in neuroblastoma metastasis to bone marrow." (PMID 37025604, 2023). "Furthermore, CXCR5/CXCL13 and CXCR1/CXCL1 interactions may specifically contribute to neuroblastoma bone marrow metastasis in part by facilitating transmigration of neuroblastoma cells through the bone marrow endothelium." (PMID 34831167, 2021).
renal cell carcinoma (4 papers, 2021 to 2025). "CXCL13 has been shown to activate mTOR signaling pathway through its interaction with CXCR5 on renal cell carcinoma." (PMID 40599793, 2025). "T cells from patients with renal cell carcinoma (RCC) exhibited multiple features of injury and depletion, as shown by the down-regulation of IL-21 expression associated with the dysfunction of CXCR5+ Tfh-like cells." (PMID 37355637, 2023). "For example, lncRNA PLK1S1 expedited renal cell carcinoma cell viability and invasion by absorbing miR‐653 and altering CXCR5 level." (PMID 35379058, 2022). "CXCR5 expression is a poor prognostic factor for renal cell carcinoma, according to qPCR and immunohistochemistry." (PMID 34922542, 2021).
schistosomiasis (4 papers, 2016 to 2021). An infectious disease caused by parasitic trematodes of the genus Schistosoma that colonize human blood vessels and release eggs that can cause granulomatous reactions leading to acute (swimmer's itch or acute schistosomiasis syndrome) or chronic disease. "CXCR5+ follicular regulatory (Tfr) cells, an especially-classified thymic-derived Foxp3+ Tregs, are reported to increase within CD4+ T cells and total Tfh cells in schistosomiasis patients." (PMID 32894174, 2020). "Using the mice model of schistosomiasis, the present study also indicated that Bcl-6+CD4+ cells would express higher CXCR5 of Tfh marker molecules than Bcl-6−CD4+ cell, the ability of Bcl-6 to up-regulate the expression of CXCR5 was strengthened in mice following S. japonicum infection." (PMID 29192177, 2017).
Splenomegaly (4 papers, 2013 to 2025). Abnormal increased size of the spleen. "In a lymphadenopathy‐prone murine model (B6/lpr), CXCR5 deletion is associated with reduced lymphadenopathy and splenomegaly." (PMID 40469525, 2025). "Compared to age- and sex-matched B6 mice, MRL/lpr mice exhibited splenomegaly with expansion of CD4+CXCR5+PD-1+ Tfh cells." (PMID 23638156, 2013).
allergic asthma (3 papers, 2018 to 2024). A asthma with a basis in a pathological type I hypersensitivity reaction. "We found a lower frequency of CXCR5+ Tfh or Tfh1 subtypes and a higher frequency of CXCR5+ICOS+ Tfh, CXCR+ICOS+PD-1+ Tfh, Tfh2 or Tfh17 subtypes in children with allergic asthma." (PMID 38424520, 2024). "As expected, the frequency of CD27+CD38+ plasmablasts, CD24hiCD38hi transitional B cells, CXCR5− Tph, CXCR5−ICOS+PD-1+ Tph, Tph2 subtypes and Tfh2 subtypes were weak positively correlated with serum total IgE level in children with allergic asthma." (PMID 38424520, 2024). "In the current study, we observed increased frequency of CXCR5− Tph, CXCR5−ICOS+ Tph, CXCR5−ICOS+PD-1+ Tph, Tph2 and Tph17 subtypes in children with allergic asthma." (PMID 38424520, 2024). "CXCR5− Tph, CXCR5−ICOS+ Tph, CXCR5−ICOS+PD-1+ Tph, CXCR5+ICOS+ Tfh and CXCR5+ICOS+PD-1+ Tfh increased in children with allergic asthma." (PMID 38424520, 2024). "First, we found a higher frequency of CXCR5− Tph, CXCR5−ICOS+ Tph and CXCR5−ICOS+PD-1+ Tph in children with allergic asthma." (PMID 38424520, 2024). "Similarly, we also found a lower frequency of CXCR5+ Tfh while a higher frequency of CXCR5+ICOS+ Tfh and CXCR+ICOS+PD-1+ Tfh in children with allergic asthma." (PMID 38424520, 2024). "Mouse models of allergic asthma and food allergy show that CXCR5+Tfh cells rather than CXCR5-Th2 cells are needed to support IgE production." (PMID 34917093, 2021). "Most interestingly, CXCR5− Tph, CXCR5−ICOS+PD-1+ Tph and Tph2 subtypes were weakly positively correlated with serum total IgE level, suggesting that CXCR5− Tph, CXCR5−ICOS+PD-1+ Tph and Tph2 subtypes may play an important role in the excessive accumulation of serum total IgE in allergic asthma." (PMID 38424520, 2024).
breast tumors (3 papers, 2015 to 2023). "A positive correlation was found between the expressions of CXCL13 and CXCR5 in breast tumors." (PMID 31354634, 2019).
CNS lymphoma (3 papers, 2020 to 2022). "Given that CNS lymphoma cells express CXCR5, it is tempting to speculate about the role of CXCL13 in the pathogenesis of CNS lymphoma." (PMID 32314548, 2020). "CXCR5, a receptor of CXCL13, was highly expressed in the CNS lymphomas." (PMID 32314548, 2020).
epilepsy (3 papers, 2020 to 2024). A brain disorder characterized by episodes of abnormally increased neuronal discharge resulting in transient episodes of sensory or motor neurological dysfunction, or psychic dysfunction. "In this study, we discovered novel functions of CXCR5 and its role in epilepsy and attempted to determine its underlying mechanism." (PMID 37460877, 2023). "Here, we found that CXCR5 deficiency affects epilepsy by contributing to impaired neuronal migration during the embryonic period." (PMID 37460877, 2023). "In summary, our results provide a clearer understanding of the expression of CXCR5 by brain region and provide a foundation for exploring its role in epilepsy as well as the putative underlying mechanisms." (PMID 37460877, 2023). "To explore why the knockdown of CXCR5 in cortical neurons leads to higher susceptibility to epilepsy, we tested neuronal excitability using whole-cell patch-clamp recording in neurons in vitro, and found that the resting membrane potential was unaffected." (PMID 37460877, 2023). "To elucidate the causal relationship between CXCR5 and epilepsy, we performed drug rescue experiments both in vivo and in vitro." (PMID 37460877, 2023). "Our data suggest that CXCR5 may promote the survival of abnormally excitable neurons resulting from developmental migration disorders, leading to increased epilepsy susceptibility." (PMID 37460877, 2023). "Combined, these findings suggested that the higher susceptibility to epilepsy in CXCR5-deficient mice may be due to increased neuronal firing that might be associated with abnormal firing patterns." (PMID 37460877, 2023). "Our results confirmed that CXCR5 gene deficiency causes abnormal neuronal development and polarity, impairs neuronal migration in late pregnancy, and ultimately increases the susceptibility to epilepsy in adulthood." (PMID 37460877, 2023). "As no spontaneous seizures were observed in mice from birth to adulthood with either loss or gain of function of the CXCR5 gene, we established KA- and PTZ-induced epilepsy models in adult mice and monitored their susceptibility to seizures." (PMID 37460877, 2023). "Secondly, we found that CXCR5 expression was increased in the cortex of humans with epilepsy but unchanged in the hippocampus of mice with KA-induced epilepsy as determined by quantitative analysis of immunofluorescence." (PMID 37460877, 2023). "Here, we first determined the expression pattern and distribution of the CXCR5 gene in the mouse brain during different stages of development and the brain tissue of patients with epilepsy." (PMID 37460877, 2023). "Next, we elucidated the effects of knocking down or overexpressing CXCR5 on seizures in two animal models of epilepsy." (PMID 37460877, 2023). "Both CXCL13 and CXCR5 were upregulated in the brain in both patients with intractable epilepsy and a rat model of epilepsy with neuroinflammation." (PMID 33161894, 2020). "The chemokine CXCL13 and its receptor CXCR5 were upregulated in epilepsy patients' brain tissue." (PMID 38361811, 2024). "In this study, we focused on the effects of CXCR5 in the development of epilepsy." (PMID 37460877, 2023). "CXCR5 expression is elevated in the brain tissue of patients with epilepsy." (PMID 37460877, 2023).
experimental autoimmune encephalomyelitis (3 papers, 2017 to 2025). An autoimmune demyelinating disease of the central nervous system that is produced experimentally in animals by the injection of homogenized brain or spinal cord in Freund's adjuvant. "CXCL13 is a ligand of CXCR5 and is found in B cell aggregates that develop in the inflamed meninges of mice with experimental autoimmune encephalomyelitis (EAE) and in humans with progressive multiple sclerosis (MS)." (PMID 31474986, 2019). "CXCR5+ T cells were detected in inflammatory infiltrates in spinal cords of mice with experimental autoimmune encephalomyelitis (EAE) and EAE was attenuated in CXCL13−/− mice." (PMID 28827539, 2017).
Granuloma (3 papers, 2014 to 2020). A compact, organized collection of mature mononuclear phagocytes, which may be but is not necessarily accompanied by accessory features such as necrosis. "It has recently been demonstrated that CXCR5+ T cell accumulate within ectopic lymphoid structures associated with TB granulomas in humans, non-human primates and mice." (PMID 25343703, 2014). "Hence, the enhanced immunosuppressive activity induced by fucoidan may be related to the functional expressions of CCR4 and CXCR5 on Treg cells, thus relieving the hepatic inflammatory response and resultant process of granuloma and fibrosis." (PMID 32894174, 2020). "This upregulation of CXCR5 on circulating ILCs reveals the importance of the CXCL13/CXCR5-axis for the migration of ILCs and further localization of ILC3 in protective lymphoid follicles within granulomas in the lung." (PMID 32887435, 2020).